ALK (ALK receptor tyrosine kinase)
Diseases named in the same sentence as ALK in open-access papers (continued):
Sharing a sentence is not in itself a finding about the gene and the disease.
cancer (continued). "It furthermore provides a rationale to exploresenescence induction as a potential therapeutic strategy in ALK-driven cancers." (PMID 21423761, 2011). "As a result, HARP and its two signalling receptors ALK and RPTPβ/ζ are now viewed as promising targets for cancer therapy." (PMID 21624116, 2011). "Like HARP, ALK is expressed during normal embryonic development in the similar pattern; however it is also overexpressed in different several human cancers." (PMID 21624116, 2011). "Comparison of ALK fusion status with results characterizing the presence of EGFR and KRAS mutations in the same set of cancer samples revealed that ALK fusions occurred in the absence of KRAS mutations." (PMID 20624322, 2010). "Genomic alterations in anaplastic lymphoma kinase (ALK) and c-ros oncogene 1 (ROS1) have been previously identified to be associated with a very high risk of VTE, whereas lower rates were reported for EGFR-mutated and ALK/ROS1/EGFR-wildtype cancers." (PMID 39858040, 2025). "The results showed that most of these dynamic resistances in DTP cancer cells could be overcome by the sequential treatment of ALK inhibitors with A-1331852 (or DT2216) and S63845 (or dinaciclib)." (PMID 40113795, 2025). "Furthermore, the biology of the underlying cancer can influence the occurrence of VTE, especially in patients with ROS proto-oncogene 1 (ROS1) fusion, anaplastic lymphoma kinase (ALK) fusion, and Kirsten rat sarcoma viral oncogene (KRAS) mutation." (PMID 40168285, 2025). "The interest in this pathway has gradually increased since the identification of two potent inhibitors, larotrectinib and entrectinib, with a wide spectrum of action and efficacy not only in NTRK altered cancer cells but also in cases where other altered genes are present, such as ALK or ROS1." (PMID 41465387, 2025). "Furthermore, despite ALK‐positive ALCL being the prototypical cancer dependent on ALK signalling, the interest of pharmaceutical companies to develop drugs towards licensing in orphan diseases seems to be limited." (PMID 40351161, 2025). "RAS mutations are considered weak as they are common in benign thyroid neoplasms and other cancers, whereas RET, NTRK, and ALK rearrangements, along with mutations in BRAF, EIF1AX, and the TERT promoter, are termed strong and are often associated with malignant tumors." (PMID 39744583, 2025). "This suggests that lorlatinib may potentially address a broader spectrum of ALK amino acid substitutions, positioning it as a promising candidate for repurposing therapies in various types of cancer." (PMID 40606598, 2025). "Additionally, terms related to signaling axes that are commonly hijacked by cancer cells, such as terms related to ALK, TROP2, and TOB1, which is a growth-suppressive factor, and EGFR and ERBB (leading genes DAB2IP and PTPRJ) were enriched in both analyses." (PMID 40564222, 2025). "A non-anticoagulant target for VTE treatment might offer a new reference for thromboprophylaxis and anticoagulation therapy for cancer patients, and it might also provide more theoretical support for a combination treatment strategy of ALK and MEK inhibitors." (PMID 37940761, 2024). "Considering the discrepancy between the liquid biopsy results and tissue immunostaining, only a small proportion of ALK fusion gene-positive cancer cells may have been present in the primary lung lesion." (PMID 39781173, 2024). "In addition to its role in cancer, ALK and its receptor family member Leukocyte tyrosine kinase receptor (LTK) have a key role in the normal physiology of the central nervous system." (PMID 39138146, 2024).
cancer (continued). "Hence, 112 RTK inhibitors were screened in KKU-M213 cells, and ceritinib, an approved targeted therapy for ALK-fusion gene driven cancers, was the most potent candidate." (PMID 38399413, 2024). "The histologic transformation of cancer cells is another mechanism of ALK-independent resistance." (PMID 38835344, 2024). "The study also explores the impact of ALK cleavage in other cancers where ALK is present and whether blocking this process could aid in devising new treatment approaches." (PMID 38397899, 2024). "The capability of ALK to induce an adaptive immune response in ALK-driven cancers could be integrated with the restoration of the innate immune system by blocking CD47-mediated DEMs within the TME." (PMID 39767726, 2024). "Therefore, we extensively validated the upregulation of CALR in a panel of ALK-positive cancer cell lines after the administration of fixed doses of TKIs, showing the overexpression of this “pro-eat me” signal at the concentrations used." (PMID 39767726, 2024). "Targeting YAP/TAZ alone or in combination with ALK could offer a promising strategy for more effective treatment of cancers involving ALK or facing resistance to ALK inhibitors." (PMID 38397899, 2024). "The introduction of targeted therapies into clinical practice paved the way for personalized medicine and improvements in the efficacy of cancer treatment but resistance remains a problem and has been reported in many studies, including those conducted with ALK TKIs2–4,41." (PMID 38653965, 2024). "ALK is an oncogene involved in the pathogenesis of various cancers." (PMID 39767726, 2024). "In pan-cancer studies, approximately 0.2–0.8% of cases were found to have ALK rearrangements." (PMID 39594806, 2024). "Furthermore, T-LAK cell-oriented protein kinase (TOPK), recognized as a potential therapeutic target in cancer, has been scrutinized in ALK+ NSCLC." (PMID 38397899, 2024). "Additionally, the rise in genes related to signaling by ALK in cancer highlights a possible oncogenic signaling hub within ESCC." (PMID 39468431, 2024). "In ALK+ cancer models, DNA vaccines directed against the ALK gene exhibited notable effectiveness." (PMID 38397899, 2024). "However, further studies are needed to evaluate the effectiveness of this approach across other ALK+ cancer subtypes, particularly in resistant cases where conventional treatment often fails." (PMID 39767726, 2024). "We investigated whether CALR surface expression was upregulated after exposure to fixed concentrations of TKIs in a panel of ALK-positive cancer cell lines available in our institution." (PMID 39767726, 2024). "Then, they showed that directly targeting diverse cancer driver mutations, including EGFR, ALK, and RAS, as well as their downstream signaling pathways, could prime cancer cells for destruction by macrophages and remodel macrophage polarization." (PMID 38690738, 2024). "Additionally, the review explores innovative directions such as ALK molecular diagnostics, ALK vaccines, and biosensors, shedding light on their promising potential within ALK-driven cancers." (PMID 38397899, 2024). "Moreover, the cancer organoids raised for this study, which are believed to be improved investigatory cancer models, also yielded compatible results, including response to targeted therapy of cancer organoid #2 which harbors ALK translocation." (PMID 38528665, 2024). "Beyond these documented effects, high-dose crizotinib therapy has been shown to trigger immunogenic cell death (ICD) in cancer cells lacking the intended ALK/ROS1 mutations, suggesting potential off-target effects beyond the drug’s primary mechanism." (PMID 39001541, 2024). "An ALK gene rearrangement was found for the first time in a de novo cancer." (PMID 38966479, 2024). "Hence, additional drug targets for combination therapy of NB and other ALK-aberrant cancers to prevent r/r disease are urgently needed." (PMID 38653965, 2024).
cancer (continued). "Similarly, a significant reduction in cell viability was observed in an A3B-knockout (KO) EML4-ALK cancer cell line (H3122) treated with the Food and Drug Administration-approved ALK TKI alectinib." (PMID 38049664, 2024). "Additionally, exploring interactions between ALK and immunotherapy and innovative methods such as ALK vaccines, biosensors, and targeted pathway approaches offers potential avenues for future interventions in ALK-driven cancers." (PMID 38397899, 2024). "Moreover, 3b inhibited the proliferation of several cancer cell lines, including ALK-addicted H2228 cells." (PMID 38465731, 2024). "This diversity makes ALK gene variations promising targets for cancer therapies." (PMID 38397899, 2024). "Additionally, “signaling by ALK in cancer” was downregulated, potentially influencing cell growth and survival." (PMID 38584841, 2024). "Furthermore, anti-ALK immunoreactivity has been observed in other types of cancer, including breast carcinoma, malignant peripheral nerve-sheath tumors, and lipogenic tumors." (PMID 38339401, 2024). "Many cancer phenotypes, including those influencing response to therapy are in addition determined by non-genetic mechanisms in addition to genetic alterations such mutations/translocations concerning BRAF, ALK and NTRK." (PMID 38357207, 2024). "Large-scale preclinical studies and clinical trials are warranted to determine whether RNase1/ALK axis inhibition and combinational immune checkpoint blockade therapy are potentially effective therapeutic strategies for all major cancer types." (PMID 38307859, 2024). "Combining TKIs with a CD47 blockade may offer therapeutic benefits in ALK+ cancers, especially in overcoming off-target resistance where TKIs alone are less effective." (PMID 39767726, 2024). "CALR overexpression seemed to be an early stress event associated with TKIs treatment in vitro, and anti-CD47 treatment could increase phagocytosis of TKIs-exposed ALK+ cancer cells." (PMID 39767726, 2024). "When the ALK gene is activated in cancer, it can lead to cell development and rapid growth." (PMID 38474400, 2024). "Clinical characteristics and outcomes and treatment patterns were assessed for 13 084 patients with NSQ cancer who had known EGFR and ALK status (75.4%; mean [SD] 62.2 [10.5] years; 6552 males [50.1%]) and all 4751 patients with SQ cancer (mean [SD] age, 67.1 [8.6] years; 4427 males [93.2%])." (PMID 38334998, 2024). "Hence, additional targets for combination treatments of NB and ALK-aberrant cancers are urgently needed." (PMID 38653965, 2024). "However, cancer cells also express PD-L1 in IFN-γ-independent manners, similar to constitutive signalling by anaplastic lymphoma kinase (ALK), EGFR mutations, and the loss of phosphatase and tensin homologs (PTEN)." (PMID 38892453, 2024). "In this instance, cancers are considered to be ALK-positive." (PMID 38254833, 2024). "Among the 10 cancer patients with ALK rearrangements, three had partial responses (PRs)." (PMID 37773318, 2023). "In ALK-positive and other rare oncogene-positive cancers, data are more limited but encouraging." (PMID 36910642, 2023). "Anaplastic lymphoma kinase (ALK; see Online Mendelian Inheritance in Man, *105590) is a receptor tyrosine kinase playing a role in regulation of cell signaling and involved in the development of many cancer types, especially NSCLC." (PMID 36817482, 2023). "Furthermore, NUMB plays a role in regulating the endocytosis of ALK (anaplastic lymphoma kinase), a receptor that is often aberrantly expressed in cancer." (PMID 36672267, 2023). "Current treatments targeting ALK mutations in other cancers, for example, have not shown significant efficacy against NB." (PMID 36839989, 2023). "IHC of the in LUAD‐OG1 organoids showed ALK was over‐expressed, and the presence of EML4‐ALK fusion variant 1 was further validated by RT‐PCR and sanger sequencing using specific fusion primers, consistent with the genotype of the parental cancer." (PMID 36709476, 2023).
cancer (continued). "However, due to consistently developed resistance to this drug, the preferred first-line treatment for ALK-positive cancers is alectinib." (PMID 37895255, 2023). "Resistance to ALK inhibitors may arise through EGFR signalling, and perhaps these cancer cells could also evade immune detection by downregulating EML4‐ALK." (PMID 37795653, 2023). "While small-molecule ALK inhibitors that target the intracytoplasmic kinase domain by binding to the ATP-binding site have been extensively studied and used for cancer treatment, their repurposing for other pathologies, such as neurological, cardiac, and metabolic diseases, has proven challenging." (PMID 37892172, 2023). "Interestingly, the aberrant ALK activity in this cancer type leads to the activation of both MAPK–ERK and PI3K–AKT–mTOR pathways." (PMID 37511126, 2023). "Furthermore, anecdotal responses of ALK fusion/rearranged cancers across a broad array of malignancies and with multiple different ALK inhibitors have been reported in 35,48,73,74,85,94,126,130–149." (PMID 37773318, 2023). "Given its pivotal role in these cancers, ALK was identified as an important therapeutic target." (PMID 37765282, 2023). "Cancer cell death in response to ALK-specific TKIs has been shown to be immunogenic." (PMID 36739466, 2023). "With advances in cancer genomics, a group of genes has been identified as drivers of LUAD, including mutations in the epidermal growth factor receptor (EGFR), c-MET, KRAS, and anaplastic lymphoma kinase (ALK)." (PMID 37511958, 2023). "Importantly, we tested the GSTP1 specific pharmacologic inhibitor ezatiostat on freshly raised cancer organoids and induced crizotinib‐resistant organoids bearing ALK fusion proteins." (PMID 36709476, 2023). "In contrast to aNSCLC patients with EGFR or ALK driver mutations, patients with KRAS G12C–positive cancer may benefit from CIT monotherapy." (PMID 37069542, 2023). "Importantly, silencing vimentin, a marker of a mesenchymal phenotype, improved the anti-cancer effects of ALK inhibitors." (PMID 37954850, 2023). "Among the 40 cfRNA samples from positive cancer patients, we could identify altered transcripts in 28; including 10 ALK, 6 ROS1, and 7 RET fusion transcripts and 5 MET∆ex14 splicing variants." (PMID 37243883, 2023). "In addition, lorlatinib is a third-generation ALK TKI that received an FDA breakthrough therapy designation in 2017 for patients whose cancer had progressed on prior ALK-directed therapy." (PMID 37895255, 2023). "Therefore, we explore effective candidates that act synergistically with ALK-TKI by screening an anti-cancer compound library." (PMID 37880373, 2023). "Anaplastic lymphoma kinase (ALK), hepatocyte growth factor receptor (HGFR/c-Met), and ROS proto-oncogene 1 receptor tyrosine kinase (ROS1) are tyrosine receptor kinases, implicated to be aberrantly expressed in human cancers." (PMID 38144528, 2023). "When activated in cancer, the cancer cells may develop and proliferate due to these ALK gene alterations." (PMID 37568193, 2023). "Our findings may contribute to a better understanding of this cancer type prior to treatment with ALK inhibitors." (PMID 37511126, 2023). "Our results support the hypothesis that the combination of SHP2 inhibition with ALK inhibition may have therapeutic potential in the treatment of ALK+ NSCLC by specifically targeting cancer cells." (PMID 37339995, 2023). "In the era of precision medicine, targeted therapies have caused a revolutionary improvement in cancer management by inhibiting activating genetic alterations in the epidermal growth factor receptor (EGFR), anaplastic lymphoma kinase (ALK), and ROS1 proto-oncogene receptor tyrosine kinase (ROS1)." (PMID 36647009, 2023). "In particular, about 30% of pediatric cancers harbor BRAF/RAS mutations, while gene fusions are present in up to 60% of cases, mainly in younger patients with PTC, usually involving RET or NTRK1/3, as also ALK, BRAF and PPARG." (PMID 37046700, 2023).
cancer (continued). "However, in the CODRP index-based drug sensitivity test, drug sensitivity was predicted as a high resistance group with a CODRP index Z-score value of ≥ 1.79 for all three ALK-targeted drugs due to high cancer stage and rapid cell growth rate." (PMID 37993887, 2023). "An understanding of these protein complexes may shed light on how the fate of nuclear NPM-ALK is regulated and, thus, how cancer stemness is regulated in ALK+ALCL cells." (PMID 37762644, 2023). "The development of cancer genomics in recent decades has permitted the identification of several gene alterations as driver gene mutations for LUAD, including anaplastic lymphoma kinase (ALK), epidermal growth factor receptor (EGFR) and KRAS." (PMID 37741993, 2023). "Anaplastic lymphoma kinase (ALK) is activated in cancer and initiates downstream STAT3 signaling." (PMID 36875139, 2023). "While the combination of the analysis of 5′/3′-end RET expression imbalance and variant-specific PCR allowed identification of RET translocations in approximately 2% of consecutive NSCLCs, this estimate approached 120/2361 (5.1%) in EGFR/KRAS/ALK/ROS1/BRAF/MET-negative carcinomas." (PMID 37445709, 2023). "Both faecal DGK and serum ALK levels are related to cancer cell growth promotion." (PMID 35202347, 2022). "Anaplastic lymphoma kinase (ALK) is a validated drug target in cancer." (PMID 36337169, 2022). "This retrospective review of NSCLC genomics data from the BC Cancer Genomic Lab Oncopanel Dataset summarizes the frequency of actionable driver mutations (EGFR, KRAS G12C, MET Exon 14 skip, ALK fusion, and ROS1 fusion), PDL-1 expression, and treatment wait times among five health authorities." (PMID 36661661, 2022). "Simultaneous inhibition of histone deacetylases (HDACs) and anaplastic lymphoma kinase (ALK) could enhance therapeutic activity against ALK addicted cancer cells." (PMID 36100230, 2022). "Anaplastic lymphoma kinase (ALK) is a receptor tyrosine kinase frequently altered in cancers, either through chromosomal translocations leading to fusion of the ALK kinase domain with the amino-terminus of other proteins, or through activating point mutations or focal gene amplifications." (PMID 35689207, 2022). "ALK fusion proteins are found in a wide range of cancer types." (PMID 35508387, 2022). "Overview of ALK-altered cell lines included in the 134 cancer cell line panel." (PMID 36185300, 2022). "In addition to the combinational therapy methods, we conceived that ALK and HDACs dual inhibitors that can concurrently inhibit both targets would be an alternative and attractive therapeutic strategy for ALK addicted cancer." (PMID 36100230, 2022). "Second, ALK was a gene involved in multiple cancer pathways." (PMID 36129915, 2022). "Compared to the selected radiomic features, diameter had no discriminative power regarding cancers with EGFR or ALK mutations, nor for histopathological types (all p > 0.050)." (PMID 35482262, 2022). "An ongoing study is screening for autologous or allogeneic T cell receptor-transgenic T cells to test against ALK+/- patient-derived and cancer cell lines using in vitro and in vivo models to assess the potential utility of cytotoxic TCR-directed immunotherapies." (PMID 35958559, 2022). "Furthermore, because of the treatment of ALK rearranged cancer, ALK has been suggested as a therapeutic target protein." (PMID 35956900, 2022). "They showed that therapeutically targeting the metabolism of this key enzyme led to the selective depletion of CDA-expressing cancer cells, a strategy that, if successful clinically, could help patients to overcome resistance to ALK-inhibiting drugs." (PMID 35999456, 2022). "Treatment with small molecule inhibitors for ALK, like ceritinib or lorlatinib, can be effective in a subset of patients, and ALK inhibitors have since entered routine and first-line therapy for many cancer entities." (PMID 35689207, 2022). "Many kinds of ALK fusion genes have been found in multiple cancer types." (PMID 35463328, 2022).